RNU5E-10P (RNA, U5E small nuclear 10, pseudogene)
Gene: Small nuclear RNA gene on chromosome 11 (47,576,471 to 47,576,588, reverse strand). Ensembl gene ENSG00000200376.
Homologues: Orthologues: chimpanzee U5 (99% identical), macaque U5 (91% identical). Paralogues in human: RNU5E-8P (81% identical), RNU5E-6P (79% identical), RNU5E-5P (75% identical), RNU5A-6P (74% identical), RNU5E-4P (74% identical), RNU5E-7P (74% identical), RNU5E-9P (74% identical), RNU5F-7P (73% identical), RNU5A-3P (72% identical), RNU5B-4P (72% identical), RNU5F-3P (72% identical), RNU5F-4P (71% identical), and 13 more.